HMGB1 (high mobility group box 1)
Diseases named in the same sentence as HMGB1 in open-access papers (continued):
Sharing a sentence is not in itself a finding about the gene and the disease.
cancer (continued). "HMGB1 provides cancer cells’ proliferation, invasion, anti-apoptotic survival, and metastatic ability." (PMID 34068442, 2021). "Taken together, our results suggest that HMGB1 potentially plays a critical role in anti-cancer immune evasion and these effects are facilitated by TLR4." (PMID 34234778, 2021). "Like exogenous HMGB1, their conditioned medium and exosomes presented cancer cell pro-survival and protective effects." (PMID 33669632, 2021). "In this model, cell damage increased HMGB1 levels, leading to the recruitment of neutrophils that subsequently promoted the migration of cancer cells toward blood vessels." (PMID 34674757, 2021). "In another study, carbon ion radiation induced an immune cell death characterized by the secretion of high mobility group box 1 (HMGB1) in human cancer cell lines." (PMID 34638376, 2021). "HMGB1 exerts dual functions in and out of cancer cells via multiple signaling pathways, such as immunity, autophagy, and inflammation." (PMID 34988076, 2021). "HMGB1 release, PD-L1 induction in the cancer cells, and PD-1 induction in the TAMs were first examined." (PMID 34488792, 2021). "A significant number of proteins characterised in our interactome, including HMGB1, were previously identified as RNA-binding proteins in cancer cells." (PMID 34572914, 2021). "In contrast, downregulation of HMGB1 inhibits cancer formation and reduces progression of the colorectal cancer." (PMID 34068442, 2021). "HMGB1 can be released into the extracellular matrix (ECM) by either granulocytes or necrotic cells to act as a cytokine/chemotaxis during cancer, infection, hypoxia, endotoxemia, and ischemia—reperfusion events." (PMID 34805222, 2021). "HMGB1 plays important roles in the genesis and promotion of a variety of inflammatory diseases, including different types of cancers." (PMID 33807620, 2021). "Those released substances and exosomes, along with exogenous HMGB1, promoted cancer cell survival and protected cells from doxorubicin cytotoxicity." (PMID 33669632, 2021). "With this clinical problem in mind, our aim was to define the role of the protein high mobility group box-1 (HMGB1) in BO and progression to cancer." (PMID 31831860, 2020). "Following ICD-inducing intervention, the release of CALR, HMGB1, and ATP by dying cancer cells is observable within hours." (PMID 33281620, 2020). "A decrease of proliferation rate in case of knockdown of the HmgB1 gene was also observed in a number of cancer lines having HmgB1 knocked down." (PMID 33114717, 2020). "In response to stimulus like bacteria or chemoradiotherapy, HMGB1 can translocate to extracellular context as a danger alarmin, activate the immune response, and participate in the regulation of inflammation and cancer progression." (PMID 32831115, 2020). "HMGB1 has been corroborated as an oncogene with respect to the initiation and progression of various cancers." (PMID 32436353, 2020). "The involvement of HMGB1 in various pathologies ranging from inflammatory diseases to cancer has been discussed thoroughly and has resulted in the development of HMGB1 secretion inhibitors." (PMID 32587593, 2020). "One of these effects is observed with doxorubicin or oxaliplatin, where the cancer cells release the alarmin high-mobility group box protein 1 (HMGB1), which acts upon the immune cell patter recognition receptors (PRR)." (PMID 33364951, 2020). "The authors observed that the levels of expression of HMGB1 correlated significantly with both clinical cancer stage and lymph node metastasis, as well as with the presence of biomarkers of Treg activation, specifically Foxp3 and IL-10." (PMID 32664328, 2020). "Ethyl pyruvate, the ethyl ester of pyruvic acid), has been shown to be an effective HMGB1-inhibitor in inflammation-related diseases and several cancers." (PMID 32443845, 2020). "Infiltrating leukocytes and cancer cells have the ability to secrete HMGB1 in response to hypoxia, injury, inflammatory stimuli, or environmental factors." (PMID 32660524, 2020).
cancer (continued). "Cell endogenous and exogenous HMGB1 therefore has different meanings, i.e., autophagy versus necroptosis, and should be considered in the autocrine communication of cancer cells during cell death." (PMID 32344698, 2020). "The multiplicity of binding partners makes the unambiguous interpretation of HMGB1 function in cancer difficult at the moment." (PMID 32698492, 2020). "Immunogenic cell death of cancer cells shortly after NIR-PIT releases damage-associated signals such as ATP, calreticulin, and high-mobility group box 1, which promotes DC maturation and subsequent effector T-cell activation mediated by IL-15." (PMID 32927646, 2020). "The role of HMGB1 in cancer development is unclear; both protumorigenic and antitumorigenic effects are considered depending on many other factors." (PMID 32684831, 2020). "Due to their stability and specificity in most bodily fluids, HMGB1 provides a high potential to serve as a liquid biopsy tool for some cancers and sterile inflammation." (PMID 33473353, 2020). "Based on the expression of both groups, it was shown that miR‐505 expression was significantly lower in cancer tissues than that in paracancerous tissues and in the serum in the SG than that in the CG; a contrasting result was obtained for HMGB1 expression." (PMID 32348630, 2020). "Elevated levels of alarmins can be seen in acute and chronic inflammatory conditions as well as certain types of cancer, especially that High Mobility Group Box 1 (HMGB1) and IL-33 are known to play roles in antitumor immune response." (PMID 32377165, 2020). "Different studies have demonstrated interaction of RAGE with a diverse range of acidic (negatively charged) ligands such as advanced glycation end products (AGEs), high-mobility group box1 (HMGB1), and S100s, and their importance to cancer progression." (PMID 32443845, 2020). "KLF4 enhances the expression of survival proteins hTERT and HMGB1 (high mobility group box 1) which sensitizes cancer cells to cisplatin cytotoxicity." (PMID 33266506, 2020). "Owing to its versatile role in cancer, HMGB1 has been proposed as a potential cancer biomarker of survival and a target for cancer therapy." (PMID 32328193, 2020). "On the other hand, intracellular HMGB1 promotes growth, invasion and resistance of cancer cells to therapy, both in vitro and in vivo." (PMID 32456685, 2020). "According to published data, self-renewal and differentiation of embryonic stem cells (ESCs), as well as growth rate of malignant tumors in animals, directly depends on the expression levels of HmgB1 and HmgB2 genes." (PMID 33114717, 2020). "HMGB1 has been previously studied in the context of a variety of human diseases, such as infectious diseases, neurodegenerative diseases, and cancer." (PMID 33384585, 2020). "HMGB1 protects cells from apoptosis because it affects telomere stability and stimulates certain cellular proteins involved in the proliferation of cancer cells." (PMID 32443845, 2020). "HMGB1 has been identified as an essential contributor towards the initiation and progression of many kinds of cancers." (PMID 33817244, 2020). "Since the half‐life of HMGB1 released by cancer cells is 3 h, the differences of the amount of HMGB1 released between the test and control samples after 1 h of mechanical vibration treatment is not negligible." (PMID 32647502, 2020). "While HMGB1 induced degradation of muscle proteins in cancer conditions by the activation of the autophagy system, the role of S100B in muscle wasting remained uninvestigated." (PMID 32159297, 2020). "In the case of HMGB1, the status of serum or tissue HMGB1 as a cancer biomarker is that of a prognostic biomarker at best." (PMID 32664328, 2020). "The release high-mobility group box1 (HMGB1) protein from tumors can also promote cancer progression." (PMID 33353113, 2020). "HMGB1 is released from dying cancer cells and enhances autophagy-induced chemoresistance and regrowth via RAGE-mediated ERK/Drp1 phosphorylation." (PMID 32660524, 2020).
cancer (continued). "Previous studies involving different cancers concluded that HMGB1 plays a paradoxical role in promoting or suppressing cancer." (PMID 33122771, 2020). "HMGB1 has been related to the onset and progression of cancer, being involved in events such as replenishing telomeric DNA and maintaining cell immortality, autophagic increase, evasion of apoptosis, as well as cell proliferation and invasion." (PMID 31694235, 2019). "Growing evidence suggests that cellular stress is associated with the unconventional secretion of proteins, highlighting among them the secretion of DAMPs, such as HMGB1 and S100s proteins, that probably connects unconventional protein secretion with cancer." (PMID 31779212, 2019). "Recently, High Mobility Group Box1 (HMGB1) protein has been reported as an inflammatory cytokine present in all nucleated cellswith crucial role in the genesis and promotion of cancer." (PMID 31485132, 2019). "High-mobility group box 1 (HMGB1), a highly conserved nuclear protein, is a positive regulator of autophagy conferring resistance to chemotherapy, radiotherapy and immunotherapy in cancer cells." (PMID 31331356, 2019). "HMGB1 is released from dying cancer cells that are undergoing necrosis, including necroptosis (programmed necrosis)." (PMID 30813267, 2019). "HMGB1 is passively released from dying or injured cells or actively secreted from cancer cells in response to exogenous and endogenous stimuli such as hypoxia and various soluble factors (TNF-α and IL-1)." (PMID 31558702, 2019). "High mobility group box B (HMGB) proteins are pivotal in the development of cancer, and HMGB1 overexpression has been related to principal cancer hallmarks." (PMID 31694235, 2019). "Stressed and dying cancer cells release endogenous “danger” signals, such as ATP, S100 and HMGB1, which bind and activate the pattern recognition receptors (PRRs), frequently TLR2 or TLR4, to trigger immune responses." (PMID 30987352, 2019). "Consistently, HMGB1 promoted CD133− cancer cells sphere forming ability was also abrogated following suppress the expression and function of TLR2." (PMID 31558702, 2019). "In a recently published study, we showed that carbenoxolone possesses anti-cancer properties mediated by its antagonistic effect on HMGB1, as demonstrated in mice that were pre-treated with the drug." (PMID 31533288, 2019). "Cancer atlas of HMGB1 protein showed up-regulated expression ofHMGB1 gene in different cancer, proved by CAB (CAB005873) and HPA-antibody (HPA003506) in silico." (PMID 31485132, 2019). "HMGB1 is expressed in all types of cells as a nuclear structural protein; however, cancer cells show RAGE activation by HMGB1, which is made available by active secretion and passive release accompanying cell death." (PMID 31905926, 2019). "HMGB1 serves as an “alarmin” that is often released from stressed and dying cells, also cancer and immune cells." (PMID 30796203, 2019). "In summary, these results indicate that extracellular HMGB1 interacts with TLR2 receptor on CD133− cancer cells to promote their dedifferentiation into CSCs." (PMID 31558702, 2019). "By means of TWAS, we recovered seven genes (APOC1, APOE, BIN1, HMGB1, PRKAA1, SQSTM1, and UCP2) significantly associated to AD traits and some cancer models." (PMID 31608105, 2019). "NSCLC tissue specimens had greater levels of HMGB1 in cancer patients with increased intratumor expression of CD8, IFN-γ, Granzyme B and Perforin." (PMID 30744691, 2019). "The functional role of HMGB1 in cancer development and progression has been reported to vary, depending upon the cell line." (PMID 31311167, 2019). "HMGB1 is a multifunctional protein that promotes cancer progression and metastasis as a ligand of RAGE or TLR4 in various malignant tumors." (PMID 31905926, 2019).
cancer (continued). "Interactome targets of HMGB1 or HMGB2 that have been identified in our Y2H study were previously found to be related to cancer hallmarks, and are also dysregulated in PCa, as confirmed by detection of changes in mRNA or protein levels." (PMID 31694235, 2019). "Recently, researchers reported that HMGB1 contributed to drug sensitivity of cancers by modulating autophagy and apoptosis." (PMID 31664305, 2019). "We found that protein instead mRNA level of HIF-1α rose in CD133− cancer cells following HMGB1 treatment in normoxia." (PMID 31558702, 2019). "Consistently, Caveolin-1 and translocation of HMGB1 significantly and consistently suppress cancer cell migration and invasion, with little effect on cell viability." (PMID 31284269, 2019). "Besides the cell division-associated genes like CCNB2 and BUB1B, we also found genes such as TPX2, BIRC5, TOP2A, SPAG5 and HMGB1, were among the top 10 highly expressed genes in the cell subset, which were reported to be directly or indirectly associated with cancer invasion." (PMID 31888172, 2019). "DAMP molecules such as calreticulin, adenosine triphosphate, or high-mobility group box 1 (HMGB1) bind to diverse surface receptors on the neighboring cancer cells and trigger further proliferation and metastasis." (PMID 31558702, 2019). "Increasing evidence suggests that HMGB1 promotes metastasis in different cancer types by using different mechanisms." (PMID 31779212, 2019). "Recent evidence suggests that the nuclear protein HMGB1 is another critical regulator of autophagy that can mediate resistance during cancer treatment." (PMID 30302772, 2019). "Silencing HMGB1 in irradiated cancer cells (feeder cells) attenuated expression levels of stem cell-related markers (Oct4, Sox2, C-myc, and Nanog) and sphere forming ability of CD133− reporter cells." (PMID 31558702, 2019). "Both TLR4 and HMGB1 are also expressed by platelets and have been shown to be another means of platelet-stimulated NETosis relevant to cancer." (PMID 31852512, 2019). "HMGB1 targeting has been identified as a potential therapeutic strategy against cancer development, progression, and in particular, metastasis." (PMID 29546074, 2018). "HMGB1 is recognized as a proinflammatory cytokine that plays a significant role in the pathogenesis of many diseases, especially inflammation disease and cancer." (PMID 30539006, 2018). "Analysis of HMGB1 expression in cancer patients demonstrated that higher expression levle of HMGB1 was detected in serum of patients who accepted radiotherapy." (PMID 29844348, 2018). "Recently, the stress-associated protein, high-mobility group protein-B1 (HMGB1), that partially serves as a regulator of autophagy has been described as harboring a prognostic impact in cancer, in particular in association with LC3B." (PMID 30134604, 2018). "This study represents a useful resource for detailed investigation of the role of HMGB1 in cancer of epithelial origins, as well as potential alternative avenues of therapeutic intervention." (PMID 29721183, 2018). "On the other hand, NETs can trigger metastasis, e.g., high-mobility group box 1 (HMGB1) released from NETs activates the TLR9-dependent pathway in cancer cells promoting their adhesion, proliferation, migration and invasion." (PMID 29250748, 2018). "Depending on the cellular localizations, the effect of HMGB1 on cancer progression is complicated and paradoxical." (PMID 29615080, 2018). "HMGB1 expression in cancer cells was upregulated following exposure to anticancer agents resulting in translocation of the protein to the cytoplasm." (PMID 30643519, 2018). "Oxidized HMGB1 also induces caspase-9/3-dependent apoptosis, resulting in sensitization to cancer therapies." (PMID 29636841, 2018). "HMGB proteins are functionally related to cancer progression and overexpression of the HMGB1 gene has been detected in cancerous cells from epithelial origin in prostate and ovary." (PMID 29721183, 2018).
cancer (continued). "The correlation between cancer tissue expressed HMGB1/HMGN1 and stromal immune cell infiltrate were then observed." (PMID 30619746, 2018). "HMGB1 overexpression has been reported in a variety of human cancers, including hepatocellular carcinoma, pancreatic cancer, leukemia, and breast cancer." (PMID 29463261, 2018). "We assume that the concentration of HMGB-1 is proportional to the density of NCs and that the density of NCs is proportional to the density of cancer cells." (PMID 29420595, 2018). "HMGB1 inhibition in the feeder supernatant significantly decreased the up-regulation effect of Zeb1 and Slug on cancer cells." (PMID 29615080, 2018). "Overall, although the role of HMGB1 in cancer therapy is complex, HMGB1 is becoming an attractive target for anticancer therapy." (PMID 30323180, 2018). "Extra- and intra-cellular high-mobility motor box 1 (HMGB1) proteins are invovled in the pathogenesis and prognosis of cancer." (PMID 30245980, 2018). "Extracellular HMGB1 decreases the expression of epithelial markers and increases the expression of mesenchymal markers in various cancer cells." (PMID 29636841, 2018). "Stressed and cancer cells release HMGB1 in the extracellular space, where it activates different receptors in a redox-sensitive manner." (PMID 30319638, 2018). "High levels of HMGB1 are always observed in various cancer types, including ovarian, liver, and lung cancers." (PMID 29568761, 2018). "Although our results appeared to be obscure statistically, which might postpone the potential application of HMGB1 as a therapeutic target as well as a prognosis predictor, reasonable confidence should be given to the null association between HMGB1 polymorphisms and risk of cancer." (PMID 30049847, 2018). "Overexpression and increased serum levels of HMGB1 have been observed in several types of cancers, including GC18,19." (PMID 29728635, 2018). "High Mobility Group Box 1 (HMGB1) is a multifunctional protein that plays various roles in the processes of inflammation, cancer, and other diseases." (PMID 29543735, 2018). "Here, we also showed that extracellular HMGB1 can impact virus spread, recovery, and act in an antiproliferative capacity during OV therapy alone or in combination with other forms of cancer treatment such as doxorubicin." (PMID 29543735, 2018). "Next, we also detected the HMGB1 mRNA levels in the 70 paired cancer samples and analyzed their correlation with TTP mRNA." (PMID 29728635, 2018). "In cancer, excessive HMGB1 release is known to contribute to angiogenesis, evasion of programmed cell death (apoptosis), inflammation, tissue invasion, and metastasis." (PMID 29636841, 2018). "Despite extensive characterization of the diverse roles of HMGB1 in cancer, much less is known about the signaling pathways of HMGB2, especially its relevance in carcinogenesis." (PMID 29463261, 2018). "Studies have found that HMGB1 is involved in inflammation and angiogenesis as well as in the invasion, progression, metastasis, and drug resistance of cancers." (PMID 30157958, 2018). "Development of anticancer drugs targeting HMGB1-induced autophagy needs to further determine the relationship between HMGB1 and autophagy against different cancer types." (PMID 30323180, 2018). "Till now, studies have correlated the HMGB1 protein to cancer progression, especially invasion and metastasis." (PMID 30049847, 2018). "First of all, we analyzed the RNA expression of HMGB1 across 17 cancer types on HPA and found that HMGB1 was widely expressed in these cancers." (PMID 29844348, 2018). "HMGB1 mediates inflammation in cancer by upregulating pro-inflammatory cytokines (such as TNF, IL-1, and IL-6) and promoting carcinogenesis." (PMID 30157958, 2018).